CCL2 (C-C motif chemokine ligand 2)
Diseases named in the same sentence as CCL2 in open-access papers (continued):
Sharing a sentence is not in itself a finding about the gene and the disease.
cognitive decline (72 papers, 2012 to 2026). "Elevated levels of CCL2, a chemokine implicated in immune cell recruitment and neuroinflammation, have been linked to microglial activation, synaptic damage, and cognitive decline in HAND." (PMID 40406114, 2025). "For example, a higher level of CCL2 in CSF was shown to be associated with faster cognitive decline during the early stages of AD55." (PMID 35974022, 2022). "Taken together, this study points towards a specific role of isoQC and pGlu-CCL2 in cognitive decline in AD and underlines the therapeutic potential of targeting the generation of pGlu-CCL2 by inhibition of isoQC." (PMID 25666182, 2015). "In AD, CCL2 was also shown to play a dominant role in chronic inflammation and to be associated with a faster rate of cognitive decline at early stages of the disease." (PMID 25666182, 2015). "CCL2 level is associated with cognitive decline, as demonstrated in aged mouse and in Alzheimer patients." (PMID 25224537, 2014). "In the present study, we show that higher baseline CCL2 levels in CSF were associated with a faster cognitive decline in patients with MCI who subsequently developed AD." (PMID 22303443, 2012). "Likewise, increased CCL2 expression has also been linked to a faster rate of cognitive decline in AD mice." (PMID 39201480, 2024). "High levels of CCL2 in patients with prodromal AD were associated with a faster cognitive decline." (PMID 35821178, 2022). "Increased CCL2 levels are associated with accelerated cognitive decline and increased risk of AD." (PMID 32415244, 2020). "Thus, higher CSF CCL2 levels are associated with a faster rate of cognitive decline and with a shorter time to conversion to dementia independent of potential confounding factors." (PMID 22303443, 2012). "Similarly, in another study CCL2 caused increased microglial accumulation, Aβ oligomerization and cognitive decline in transgenic AD mice." (PMID 22303443, 2012). "MIP1A/CCL3 and eotaxin/CCL11 are linked to AD, MCP1/CCL2 levels correlate with neuroinflammation, brain atrophy, and cognitive decline in AD, and MCP3/CCL7 is part of a diagnostic panel for AD." (PMID 39574895, 2024). "Clinical trial results ultimately confirmed that NPSLE patients exhibiting elevated CCL2 expression also experienced cognitive decline." (PMID 39403387, 2024). "Previously, studies have reported increased CCL2 expression in the cerebrospinal fluid of patients with AD and HAND in association with cognitive decline." (PMID 32103758, 2020). "It has also been reported that increased CSF CCL2 levels at baseline in patients with prodromal AD correlated with a faster cognitive decline during the study's follow-up period." (PMID 25340798, 2014). "Other methods are needed to reflect the stage of the disease and the rate of cognitive decline and the present study suggest that CSF CCL2 is a candidate biomarker for future disease progression rate in prodromal AD." (PMID 22303443, 2012). "In subjects with MCI, cerebrospinal fluid and plasma levels of CCL2 are significantly elevated, and CCL2 may serve as a prognostic biomarker for the rate of cognitive decline in patients with MCI." (PMID 39011039, 2024). "Human studies have shown that higher CCR2 expression correlates with poorer cognitive function, suggesting a direct involvement of CCR2 in human cognition, possibly due to enhanced CCL2 expression in brain microglia and macrophages, indicating a link to age-related cognitive decline." (PMID 39201480, 2024). "The Fg-induced CCL2 upregulation in neurons that we found in the current study might be the bridge that connects a pro-inflammatory state to cognitive decline, as we and others have found." (PMID 36551169, 2022). "In APP mice, overexpression of CCL2 results in increased deposition of Aβ in the cerebral cortex and hippocampus, coinciding with enhanced accumulation of mononuclear phagocytes around senile plaques, and leading to cognitive decline." (PMID 35821178, 2022).
cognitive decline (continued). "An additional consideration when interpreting the longitudinal role of peripheral MCP-1/CCL2 levels on cognitive decline is the mechanism by which the periphery might induce changes in the CNS." (PMID 30814948, 2019). "We therefore investigated whether CCL2 could be used in combination with these standard CSF biomarkers to predict future cognitive decline in the whole MCI cohort." (PMID 22303443, 2012). "Furthermore, prodromal AD patients in the highest tertile of CSF CCL2 exhibited a significantly faster cognitive decline (p<0.001) and developed AD dementia within a shorter time period (p<0.003) compared to those in the lowest tertile." (PMID 22303443, 2012). "However, in patients with prodromal AD, the CCL2 levels in CSF at baseline correlated with a faster cognitive decline during follow-up (rs = 0.42, p = 0.004)." (PMID 22303443, 2012). "Importantly, the subgroup with both an AD-indicative (pathological) CSF biomarker pattern and higher CCL2 levels in CSF at baseline exhibited a significantly faster cognitive decline during follow-up than the other subgroups." (PMID 22303443, 2012). "If our results are corroborated by other studies, CSF CCL2 could be used when predicting the future rate of cognitive decline in patients with prodromal AD." (PMID 22303443, 2012). "Ccl2, which encodes for monocyte chemoattractant protein-1 (MCP-1), showed a greater than two-fold elevation in aged rat cortex, and in other studies has been linked to AD-associated cognitive decline, tauopathy, and age-related BBB endothelial cell dysfunction." (PMID 35798912, 2022). "This process enhances the production of inflammatory mediators such as IL-1β, IL-6, IFN-γ, TNF-α, CCL2, GMF, NO, and ROS, ultimately driving inflammatory responses and cognitive decline in neurodegenerative diseases." (PMID 40556958, 2025). "As such, mouse models of amyloidosis deficient in CCR2 exhibited exacerbation of cognitive decline and amyloid pathology; however, the role of CCR2/CCL2 axis in tauopathy was never substantiated." (PMID 34172073, 2021).
bladder cancer (69 papers, 2011 to 2026). "In bladder cancer, CCL2/CCR2 interaction has been implicated in the stimulation of lymphoangiogenesis and development of lymphatic metastasis via macrophage tumor infiltration and VEGF-c production." (PMID 31811337, 2020). "An understanding of the molecular mechanisms underlying the sustained expression of CCL2 in bladder cancer could provide a novel theoretical basis for the development of effective anti-CCL2 therapies." (PMID 37915048, 2023). "Therefore, we investigated the impact of FAM171B/CCL2 modulation on bladder cancer-associated macrophage polarization both in vivo and in vitro using double immunofluorescence staining and flow cytometry." (PMID 37915048, 2023). "Thus, exploring the precise molecular mechanism underlying sustained CCL2 expression in bladder cancer would provide a potential predictor of effective anti-CCL2 treatment." (PMID 30237493, 2018). "Therefore, exploring the biological characters and molecular mechanisms underlying sustained CCL2 expression in bladder cancer may provide clinically predictive tools for effective anti-CCL2 treatments." (PMID 30237493, 2018). "The level of circRIP2 in bladder cancer patients is correlated with clinical prognosis, and chemokine (C-C motif) ligand 2 (CCL2) is differentially expressed in circRIP2 overexpressed cells." (PMID 40296917, 2025). "CCL2 inhibition in mouse models of bladder cancer in situ has been shown to inhibit tumor growth, reduce MDSCs and TPCs, and promote tumor immunosuppression." (PMID 39790460, 2025). "This process increases the secretion of CCL2 and IL-13 by bladder cancer cells, thereby promoting the polarization of monocytes into TAMs." (PMID 41425713, 2025). "Specifically, chemokine (C-C motif) ligand 2 (CCL2) plays a crucial role in recruiting TAMs and contributes to bladder cancer cell proliferation, metastasis, and the establishment of an immunosuppressive environment in the TME." (PMID 38542078, 2024). "It has been found that CCL2 overexpression in bladder cancer is due to the FAM171B protein, which can act as an immune regulator and upregulate CCL2 expression." (PMID 38542078, 2024). "KEGG gene enrichment analysis of Mast-CCL2 showed a high enrichment in bladder cancer signaling and Toll-like receptor signaling pathways." (PMID 39308672, 2024). "From the human data, the urine of bladder cancer patients had significantly upregulated levels of CCL2, IL-6, CXCL10, IL-1b, IFN-g, TGF-b, and IL-8 in comparison to the healthy donors." (PMID 37901214, 2023). "By this means, LNMAT1 recruits HNRNPL to the CCL2 promoter and activates its transcription in the nucleus of bladder cancer cells." (PMID 37407839, 2023). "CCL2 activation and subsequent secretion by bladder cancer cells in turn upregulates VEGF-C expression in tumor-associated macrophages, promoting lymphangiogenesis and lymphatic metastasis." (PMID 37407839, 2023). "The levels of IL-6, IL-10, CCL2 were significantly decreased in both two bladder cancer cell lines, and Other transcription factors are uncertain in cell lines." (PMID 35769470, 2022). "In this investigation, we found that silencing IQGAP2 increased IL-6 and CCL2 levels in bladder cancer cells, whereas the overexpression of IQGAP2 lowered IL-6, IL-8, and CCL2 levels." (PMID 36362301, 2022). "Mechanistically, LNMAT1 epigenetically activates CCL2 expression and recruits macrophages into bladder cancer, which promotes lymphatic metastasis via VEGF-C excretion." (PMID 34733886, 2021). "A study of bladder cancer found that lymph node metastasis-related transcripts expressed by tumor cells 1 can recruit heterologous ribonucleoprotein to the CCL2 promoter to activate CCL2 expression." (PMID 33391402, 2021). "LNMAT1 promoted the lymphatic metastasis of bladder cancer via CCL2-dependent macrophage recruitment." (PMID 34093798, 2021).
bladder cancer (continued). "Several studies demonstrated overexpression of CCL2 in bladder cancer was correlated with tumor invasion, tumor progression and lymphatic metastasis." (PMID 34893045, 2021). "Mast cells in tumor microenvironment were reported to strengthen bladder cancer metastasis by regulating ERβ/CCL2/CCR2 EMT/MMP9 signals." (PMID 34112144, 2021). "Autocrine CCL2 enhances the infiltration and migration of the bladder cancer cell line MBT2 by PKC activation and tyrosine phosphorylation." (PMID 34445235, 2021). "This increases CCL2 secretion in bladder cancer cells, mobilizes TAMs to cancer tissue, and promotes lymph node metastasis." (PMID 34445235, 2021). "In bladder cancer, myeloid cells isolated from peripheral blood secreted significant amounts of CCL2 constitutively." (PMID 31811337, 2020). "LNMAT1 epigenetically activates CCL2 expression by recruiting hnRNPL to the CCL2 promoter in bladder cancer." (PMID 32019566, 2020). "Another study demonstrated that CCL2 plays a role in macrophage recruitment that regulates lymphatic metastasis of bladder cancer." (PMID 32986377, 2020). "Examining CCL2 levels in urine samples from 60 bladder cancer patients and 20 control healthy subjects revealed CCL2 levels in the urine of patients with bladder cancer correlated significantly with TNM stage and cancer grade." (PMID 33297571, 2020). "LNMAT1-induced CCL2 in bladder cancer cells contributes to recruit macrophages into the tumor and ultimately promotes lymphatic metastasis of bladder cancer." (PMID 32549757, 2020). "For example, CCL2 (chemokine C-C motif ligand 2) is produced primarily by a variety of tumor cells, including bladder cancer 40, and is critical for cancer metastasis." (PMID 31777603, 2019). "We found that CCL2 was markedly overexpressed in bladder cancer tissues compared with the paired NATs and that CCL2 levels were positively correlated with LN metastasis (p < 0.01)." (PMID 30237493, 2018). "Here they demonstrate that a long noncoding RNA LNMAT1 promotes LN metastasis of bladder cancer via recruitment of TAMs through epigenetic regulation of CCL2 expression." (PMID 30237493, 2018). "Consistent with previous reports, CCL2 inhibition significantly inhibited the migratory capability of bladder cancer cells." (PMID 30237493, 2018). "We further showed that increased TAMs infiltration, which produced higher levels of VEGF-C that promotes lymphangiogenesis and the formation of lymphatic metastasis, was induced by CCL2 secreted by bladder cancer cells." (PMID 30237493, 2018). "Next, the regulatory effect of hnRNPL on CCL2 expression was examined with ELISA and qRT-PCR assays, which showed that CCL2 expression was decreased in hnRNPL-silenced bladder cancer cells." (PMID 30237493, 2018). "In this study, we demonstrated that LNMAT1 epigenetically upregulated CCL2 expression in bladder cancer cells by interacting with hnRNPL to promote H3K4me3 of the CCL2 promoter." (PMID 30237493, 2018). "Consistently, TCGA data analysis showed that the elevated expression of CCL2 was correlated with LN metastasis, higher tumor grade and poorer OS of bladder cancer." (PMID 30237493, 2018). "So globally, mast cells promote metastasis of bladder cancer in mice in a CCL2/CCR2/EMT/MMP9‐dependent mechanism." (PMID 28599100, 2017). "The significance of tumor expression of the proteoglycan versican and chemokine CCL2 (also known as MCP1) in promoting bladder cancer lung metastasis was investigated using syngeneic MB49 metastatic model." (PMID 28915710, 2017). "Of these, NQO1, CCL2, and MDM2 are associated with increased risk or tumor promoting function in bladder cancer." (PMID 28122346, 2017). "It has been shown that when mast cells are co‐cultured with bladder cancer cells, CCL2 expression is elevated (after ERβ decrease) and EMT is activated in cancer cells, which express MMP‐9 and display enhanced invasive properties." (PMID 28599100, 2017).
bladder cancer (continued). "Also, the release of CCL2, CXCL1, and Il-6 by CAAs is associated with bladder cancer cell migration." (PMID 40076892, 2025). "Furthermore, MCs enhance interactions between estrogen receptors (ERs) and CCL2 within tumors, facilitating bladder cancer invasion through the MC–ER–CCL2 axis, which promotes epithelial-mesenchymal transition (EMT) and matrix metalloproteinase (MMP) activity." (PMID 41425713, 2025). "Targeting CCL2 inhibits the proliferation and invasion of bladder cancer cells." (PMID 41341593, 2025). "Furthermore, preclinical bladder cancer models suggest inhibition of macrophage recruitment via blockage of CCL2 can lead to a reduction of lymph node metastases and increased survival after chemotherapy." (PMID 36793050, 2023). "Therefore, we conducted in vivo and in vitro experiments to investigate the effects of FAM171B and HNRNPU on CCL2 expression in bladder cancer cells." (PMID 37915048, 2023). "In recent years, some studies have demonstrated that CCL2 can be considered as an independent prognostic factor for bladder cancer, clear-cell renal cell carcinoma, and gastric cancer, together with our findings, further highlighting a significant value of CCL2 in human cancer prognosis." (PMID 38057698, 2023). "It is known that the presence of single nucleotide polymorphisms (SNP) of the CCL2 gene is associated with breast, oral, endometrial, non-small cell lung, prostate and bladder cancers." (PMID 36341366, 2022). "Moreover, cisplatin-resistant bladder cancer cells recruit MDSCs by secreting chemokines, including CCL2, to avoid attack from cytotoxic T lymphocytes." (PMID 34445235, 2021). "Besides, animal experiment also proved the increased CCL2 expression in murine bladder cancer cell line." (PMID 34893045, 2021). "Lymph node metastasis-associated transcript 1 (LNMAT1), a long-chain non-coding RNA, is significantly up-regulated in bladder cancer cells to enhance the transcription of CCL2, thereby recruiting TAMs to produce VEGF-C which promotes bladder cancer-associated lymphatic metastasis of tumors." (PMID 33224886, 2020). "LncRNA LNMAT1-induced CCL2 recruits TAMs, leading to lymphatic metastasis of bladder cancer." (PMID 31448238, 2019). "Furthermore, LNMAT1-induced CCL2 expression by bladder cancer cells recruited TAMs, which participated in the pro-lymphangiogenic process via VEGF-C excretion and ultimately contributed to lymphangiogenesis and lymphatic metastasis." (PMID 30237493, 2018). "Understanding the precise role of LNMAT1 in the LN metastasis of bladder cancer and in activation of the CCL2/TAMs axis will not only increase our knowledge of lncRNA-induced LN metastasis but also enable the development of a therapeutic strategy for bladder cancer LN metastasis." (PMID 30237493, 2018). "By acting on endothelin-1 (ET-1) receptor, tumor-derived ET-1 induced the migration of both tumor cells and macrophages into lungs and also induced the expression of pro-inflammatory cytokines including IL-6 and CCL2 in several bladder cancer lung metastasis models." (PMID 30597969, 2018). "In summary, our study provides solid evidence supporting the hypothesis that LNMAT1 overexpression is clinically and functionally relevant to the lymphatic metastasis of human bladder cancer via CCL2-mediated modulation of the tumor microenvironment." (PMID 30237493, 2018). "Moreover, overexpression of the truncated LNMAT1 (350–550 nt) in LNMAT1-silenced bladder cancer cells restored the CCL2 upregulation function of LNMAT1." (PMID 30237493, 2018). "Consistently, silencing CCL2 also only moderately reduced the LN-metastatic capability of vector-control bladder cancer cells (from 31.25% reduced to 18.75%) but remarkably inhibited the LN-metastatic capability of LNMAT1-overexpressing cells (from 81.25 to 12.50%)." (PMID 30237493, 2018). "Collectively, our results suggest that LNMAT1 induce CCL2 expression in bladder cancer." (PMID 30237493, 2018).